PBX1 (PBX homeobox 1)
Diseases named in the same sentence as PBX1 in open-access papers (continued):
Sharing a sentence is not in itself a finding about the gene and the disease.
colorectal cancer (6 papers, 2022 to 2026). A primary or metastatic malignant neoplasm that affects the colon or rectum. "Pre-B-cell leukemia homeobox 1 (PBX1) is a transcription factor involved in diverse cellular processes, but its role in colorectal cancer (CRC) remains incompletely understood." (PMID 42086530, 2026). "On the other hand, in colorectal cancer PBX1 functions as a tumor suppressor, highlighting its context-dependent role." (PMID 38404687, 2024). "The order results of PBX1 showed higher expression levels in normal colon tissues than in colorectal cancer tissues." (PMID 36739270, 2023). "It has been reported that PBX1 was inhibited in colorectal cancer." (PMID 39129784, 2024). "Overall, PBX1 is downregulated in colorectal cancer and may function as an antioncogene that controls cell proliferation and stemness." (PMID 36739270, 2023). "Studies have revealed that PBX3, the homologous family protein of PBX1, promoted the migration and invasion of glioblastoma and colorectal cancer via activation of the MAPK/ERK signaling pathway, which might bring new insights into the oncogenic role of PBX1 in NSCLC." (PMID 36361531, 2022). "The promoting and inhibiting function of PBX1 in various cancer types was extensively discussed, however, there have been no studies on PBX1 proteins in colorectal cancer (CRC)." (PMID 36739270, 2023). "However, there have been no studies on the role of PBX1 in colorectal cancer progression." (PMID 36739270, 2023).
melanoma (6 papers, 2013 to 2025). A malignant, usually aggressive tumor composed of atypical, neoplastic melanocytes. "Moreover, PBX1 interacts with HOXB7 in melanoma cells and the downregulation of Pbx1 causes Hoxb7 and target gene downregulation, including bFGF, Ang-2, and Mmp9." (PMID 33402862, 2020). "In the metastatic melanoma cell line, both mRNA and protein expression analysis has shown that Pbx2 expression was elevated when compared to Pbx1, Pbx3, and Pbx4." (PMID 33402862, 2020). "The analysis of the PBX family mRNAs (PBX1 to 4) in the metastatic melanoma cell line A375M confirmed PBX2 principal expression (top)." (PMID 23400877, 2013). "Moreover, inactivation of PBX1 by specific small interfering RNA or blockade of the PBX1 promoter region G-4 quadruplex structure by small molecule inhibitors can significantly suppress the growth of melanoma cells." (PMID 39129784, 2024). "Notably, PBX1 is highly expressed in melanoma cells, and its restorative expression can counteract the growth inhibition mediated by the promyelocytic leukemia zinc-finger protein." (PMID 39129784, 2024). "Pbx1 is downregulated by promyelocytic leukemia zinc-finger (PLZF) protein in melanoma cells." (PMID 33402862, 2020). "Our data are supported by findings in osteosarcoma and melanoma, showing that HOXB9 and PBX1, respectively, contribute to SPP1 activation in these tumours." (PMID 40149711, 2025). "In view of the requirement of HOX cofactors, such as PBX proteins, for HOXB7 oncogenic activity, we measured the levels of PBX1 and PBX2 proteins in melanoma cell lines, representative of early and advanced stages, showing that PBX2 protein was more abundant than PBX1 (bottom)." (PMID 23400877, 2013).
neuroblastoma (6 papers, 2019 to 2024). Neuroblastoma (NB) is the most common solid, extracranial childhood tumor. "In addition to the prognostic importance of PBX1, NF1, and HOXC9 proteins, our results demonstrated that PBX1 could be used for the prediction of the clinical response to induction chemotherapy in patients suffering from high-risk neuroblastoma." (PMID 31803613, 2019). "PBX1 expression served as predictive biomarker in neuroblastoma cells to distinguish between sensitivity and resistance to retinoids." (PMID 35068042, 2022). "Furthermore, PBX1 expression is reduced in neuroblastoma in response to ATRA and other retinoids." (PMID 35743243, 2022). "RNA sequencing results showed a synergistic induction of genes associated with RA signaling (RARB, RARG), neuronal differentiation (HOXC5, PBX1), and chromatin remodeling (RYBP, JADE2), which are positively correlated with favorable prognosis in neuroblastoma." (PMID 39711563, 2024). "Moreover, our results from survival analyses reveal the prognostic value of PBX1, NF1, and HOXC9 expression in neuroblastoma tissue." (PMID 31803613, 2019).
pancreatic cancer (6 papers, 2016 to 2024). "It was found that miR-198 transcription is reduced in pancreatic cancer and that miR-198 inhibition increases PBX-1 and VCP expression; dysregulation of the PBX-1/VCP axis enhances tumorigenicity." (PMID 39129784, 2024). "Overexpression of miR‐198 in pancreatic cancer cells inhibited tumour growth, metastasis, and promoted survival by directly targeting PBX‐1, MSLN, and VCP." (PMID 35068042, 2022). "In pancreatic cancer, reconstitution of miR-198 resulted in reduced tumor growth and metastasis through direct targeting MSLN, PBX-1, and VCP." (PMID 26852230, 2016).
acute myeloid leukemia (5 papers, 2010 to 2024). Acute myeloid leukemia (AML) is a group of neoplasms arising from precursor cells committed to the myeloid cell-line differentiation. "Some studies have suggested that it is necessary since the HCM domain of PBX1, which mediates HOX protein interaction, is required for fibroblast transformation in vitro, blocked differentiation of cultured murine myeloid progenitors, and acute myeloid leukemia in mice." (PMID 30894657, 2019).
developmental delay (5 papers, 2017 to 2024). "Developmental delays and craniofacial dysmorphy were also reported in patients who carried PBX1 gene mutations or deletions." (PMID 36544198, 2022). "PBX1 mutations lead to congenital kidney and urinary tract anomalies with or without hearing loss, abnormal ears, or developmental delay." (PMID 32552830, 2020). "The second region involves PBX1 (OMIM #176310) at chromosome region 1q23.3, which is also associated with an autosomal dominant neurodevelopmental disorder: congenital anomalies of kidney and urinary tract syndrome with or without hearing loss, abnormal ears or developmental delay (OMIM #617641)." (PMID 36430143, 2022).
myoepithelial tumor (5 papers, 2015 to 2024). A benign or malignant tumor characterized by the presence of cells that show myoepithelial differentiation. "This was because PBX3 has extensive homology to PBX1 which has been found as a 3 ́-partner in an EWSR1-PBX1 fusion in myoepithelial tumors." (PMID 25875009, 2015). "Chondroid syringomas are considered a cutaneous part of myoepithelial neoplasms that show a variety of genetic alterations, such as gene fusion of EWSR1 with PBX1 in soft tissue originated tumors." (PMID 35225876, 2022).
CNS leukemia (4 papers, 2016 to 2024). "Moreover, 50% of the relapsed children had BCR::ABL1 or TCF3:: PBX1 fusion genes as a high-risk factor for CNS leukemia relapse, consistent with literature reports." (PMID 38519960, 2024).
esophageal cancer (4 papers, 2011 to 2023). A primary or metastatic malignant neoplasm involving the esophagus. "The dysregulation of PBX1 has been reported for ovarian, prostate, and esophageal cancer." (PMID 35041720, 2022).
glioma (4 papers, 2020 to 2024). A benign or malignant brain and spinal cord tumor that arises from glial cells (astrocytes, oligodendrocytes, ependymal cells). "The YTHDC1/circPOLR2B/POLR2B/PBX1 axis plays a regulatory role in the biological behavior of GSCs, offering potential targets and novel strategies for the treatment of glioma." (PMID 39090090, 2024).
Hodgkins lymphoma (4 papers, 2021 to 2024). A heterogeneous group of malignant lymphoid neoplasms of B-cell origin characterized histologically by the presence of Hodgkin and Reed-Sternberg (HRS) cells in the vast majority of cases. "In accordance with these physiological data, the aberrant maintenance of PBX1 activity in developing B-cells contributes to the generation of pre-B-cell leukemia or Hodgkin lymphoma." (PMID 35328612, 2022). "PBX1 was upregulated in Hodgkin lymphoma and affected the differentiation of Hodgkin lymphoma cells by activating NFIB and TLX2." (PMID 35068042, 2022). "Accordingly, we also described the lymphoid TALE-code and applied that gene signature to identify the aberrant activity of TALE homeobox gene PBX1 in Hodgkin lymphoma." (PMID 35328612, 2022).
myeloproliferative neoplasm (4 papers, 2023 to 2025). A clonal hematopoietic stem cell disorder, characterized by proliferation in the bone marrow of one or more of the myeloid (i.e., granulocytic, erythroid, megakaryocytic, and mast cell) lineages. "This target utilisation has been observed to influence Myeloproliferative neoplasm (MPN) cells via PBX1." (PMID 39239563, 2024). "PBX1 may contribute to other hematopoietic cancers also in the absence of genomic alterations, for example, if overexpressed or if expressed in HSCs or MEPs in the presence of other driver mutations, such as the somatic V617F mutation in the JAK2 gene typical of myeloproliferative neoplasm (MPN)." (PMID 38404687, 2024).
type 2 diabetes (4 papers, 2006 to 2023). "We had more power to identify causality from DNAm to type 2 diabetes than in the reverse direction, for which PBX1 was the signal most likely to be associated with type 2 diabetes." (PMID 37202507, 2023). "Using forward 2SMR, we observed evidence of causality (adjusted p<0.001 or unadjusted p<0.05) between type 2 diabetes and lower levels of DNAm at the CpGs cg20812370 (PBX1) (p=0.002) and cg01577083 (RBFOX1) (p=0.023)." (PMID 37202507, 2023). "We tested 39 SNPs spanning the PBX1 locus for association with type 2 diabetes in 3,093 French subjects." (PMID 18312624, 2008). "We have examined a number of common SNPs spanning the PBX1 locus for association with type 2 diabetes in the French population and obtained several nominal association signals, of which the strongest was the intron 2 SNP rs2792248." (PMID 18312624, 2008). "In the present study, we set out to perform a large association study of common PBX1 variation and type 2 diabetes in French Caucasians." (PMID 18312624, 2008). "Employing a case-control design, we genotyped 39 SNPs spanning the PBX1 locus in 3,093 subjects to test for association with type 2 diabetes." (PMID 18312624, 2008). "The availability of data from type 2 diabetes genome-wide association studies (GWASs) prompted us to carry out a meta-analysis of PBX1 variants genotyped in common between the present study and the GWASs." (PMID 18312624, 2008). "The aim of this study was to evaluate the association of common PBX1 variants with type 2 diabetes in French Caucasian subjects." (PMID 18312624, 2008). "Several PBX1 SNPs, including the G21S coding SNP rs2275558, were nominally associated with type 2 diabetes but the strongest result was obtained with the intron 2 SNP rs2792248 (P = 0.004, OR 1.20 [95% CI 1.06–1.37])." (PMID 18312624, 2008). "PBX1 is essential for normal pancreatic development and function and has shown a modest association to Type 2 diabetes susceptibility in humans." (PMID 16542463, 2006). "PBX1 SNPs nominally associated with type 2 diabetes in French Caucasians." (PMID 18312624, 2008). "Before formally rejecting PBX1 as a type 2 diabetes susceptibility gene, however, we should make the point that PBX1 is a large gene and the current study does not provide comprehensive coverage of common variation at the PBX1 locus." (PMID 18312624, 2008). "Several PBX1 SNPs, including the G21S variant, were modestly associated with type 2 diabetes, but the strongest result was obtained with the intron 2 SNP rs2792248 (P = 0.004, OR 1.21 [95% CI 1.06–1.39]), which had shown preliminary association with type 2 diabetes in the 1q Consortium dataset." (PMID 18312624, 2008). "PBX1 is a biological candidate gene for type 2 diabetes at the 1q21-q24 susceptibility locus." (PMID 18312624, 2008). "Examination of Pbx1+/− mice has also shown that this transcription factor is required for pancreatic insulin secretion in mature islets, as Pbx1 inactivation causes reduction of circulating insulin levels and impaired glucose tolerance, conditions known to presage the onset of overt type 2 diabetes." (PMID 30002646, 2018). "For comparison, CpGs that were likely to be secondary to the effects of type 2 diabetes (in PBX1, SPEG, MIR657 and RBFOX1) based on the results of the 2SMR analysis were enriched for perinatal and neurological traits in addition to cardiometabolic and anthropometric traits." (PMID 37202507, 2023). "Nevertheless, our results are in general agreement with the type 2 diabetes GWASs, none of which found strong association signals at PBX1 or indeed anywhere within the 1q region." (PMID 18312624, 2008). "The available data does not support a major influence of common PBX1 variants on type 2 diabetes susceptibility or quantitative metabolic traits." (PMID 18312624, 2008). "The available data do not support a major influence of common PBX1 variants on type 2 diabetes susceptibility or quantitative metabolic traits." (PMID 18312624, 2008).
type 2 diabetes (continued). "Finally, none of the PBX1 SNPs nominally associated with type 2 diabetes were associated with a range of metabolic quantitative traits in the normoglycemic control subjects." (PMID 18312624, 2008). "For associations at cg20812370 (PBX1) and cg01577083 (RBFOX1), there was little evidence of heterogeneity in the effect of 62 type 2 diabetes SNPs on DNAm levels based on the results of the Cochran’s Q test (Q range 52.9–74.8, p value range 0.10–0.75)." (PMID 37202507, 2023).
anemia (3 papers, 2012 to 2022). A reduction in the number of red blood cells, the amount of hemoglobin, and/or the volume of packed red blood cells. "BPTF knockout leads to defects like anemia by suppressing Meis1, Pbx1, Mn1, and Lmo2 genes required for self-renewal." (PMID 35399522, 2022). "Pbx1−/− embryos exhibit profound anemia and decrease in common myeloid progenitor cells in the fetal liver; Pbx1 is also essential for generation of common lymphoid progenitors and maintenance of LT-HSC." (PMID 23133585, 2012). "Lack of Pbx1 has been associated with severe fetal anemia and disruption in lymphoid differentiation since the absence of Pbx1 leads to premature expression of ST-HSCs genes within LT-HSCs." (PMID 35399522, 2022). "Furthermore, PBX1 (Pre-B-cell leukemia homeobox-1) is necessary for the maintenance of definitive hematopoiesis in the fetal liver, which indicates the host-protective role of PBX1 from anaemia and thus contributing to trypanotolerance of N’Dama." (PMID 33429951, 2021).
bladder cancer (3 papers, 2023 to 2025). "The association between PBX1 and estrogen signaling was also confirmed in the estrogen-mediated bladder cancer, in which PBX1 expression levels were positively related to tumor size, lymph node metastasis and poorer survival." (PMID 38404687, 2024). "Pre-B-cell leukemia transcription factor 1 (PBX1), a transcription factor known to involve cancer cell proliferation, apoptosis, and EMT, has been implicated in ER signaling in bladder cancer." (PMID 40486871, 2025). "Both ERα and ERβ were shown to interact with PBX1 in bladder cancer cells, which was required for ER function." (PMID 40486871, 2025). "Overexpression of PBX1, which could interact with both ERα and ERβ, was also shown to reduce the cisplatin cytotoxicity in bladder cancer cells." (PMID 40486871, 2025).
Cerebral ischemia (3 papers, 2016 to 2026). Restriction of arterial blood supply to the brain associated with insufficient oxygenation to support the metabolic requirements of the tissue. "In neurological contexts, miR‐141‐3p participates in regulating neural stem cell neurogenesis and modulates neuronal apoptosis by targeting PBX1 to regulate PROK2 transcription in cerebral ischemia models." (PMID 41523988, 2026). "The experimental results indicated that PBX1 and ATF1, along with six other TFs, are putative target TFs for DHI-mediated protection against cerebral ischemia." (PMID 27431009, 2016).
clear cell renal carcinoma (3 papers, 2022 to 2023). A malignant epithelial neoplasm of the kidney characterized by the presence of lipid-containing clear cells within a vascular network. "The “Oncomine” database shows that abnormal PBX1 overexpression exists in numerous cancer categories, including renal clear cell carcinomas (ccRCCs), accounting for 70% of renal tumors." (PMID 37006624, 2023). "Similarly, the cycle regulator CyclinD1 was maintained as a target gene of the JAK2/STAT3 signaling pathway subjected to the regulation of PBX1 in clear cell renal carcinoma." (PMID 36361531, 2022). "In addition, a study revealed that another cell cycle regulator CyclinD1 was subjected to the regulation of transcription factor PBX1 in clear cell renal carcinoma." (PMID 36361531, 2022).
cryptorchidism (3 papers, 2023 to 2025). The failure of one or both testes of a male fetus to descend from the abdomen into the scrotum during the late part of pregnancy. "Reverse phenotyping identified cryptorchidism and dysmorphic external ears, both of which are extrarenal manifestations commonly associated with PBX1-related CAKUT." (PMID 41255624, 2025). "Interestingly, some patients (especially 46,XY individuals with PBX1 missense mutations) presented with DSDs ranging from cryptorchidism and a micropenis to complete sex reversal, a phenotype that is not fully recalled by murine PBX1-KO models." (PMID 36833200, 2023). "The data indicated that the interaction of PBX1 with different partners such as the HOX genes is responsible for abnormal proliferation and variation of the embryonic mesenchyme, while truncating variants were shown to cause milder phenotypes (mostly cryptorchidism and deafness)." (PMID 37006624, 2023).
diabetes (3 papers, 2018 to 2026). "Pbx1 is necessary for renal development and is involved in the activation of the nephrin promoter in the proximal tubules, while Nrf1 acts as a cytoprotective factor in cells and plays a regulatory role in diabetes by modulating the level of glutathione." (PMID 37827693, 2023). "Experiments performed in mutant mice have shown that while the single Pbx1 or Pdx-1 knockout mice feature pancreatic islet malformations, impaired glucose tolerance and hypoinsulinemia, the trans-heterozygous Pbx1+/−Pdx1+/− mice develop age-dependent overt diabetes mellitus." (PMID 30002646, 2018).
lung adenocarcinoma (3 papers, 2013 to 2023). A carcinoma that arises from the lung and is characterized by the presence of malignant glandular epithelial cells. "The synonymous mutation (c.1299C>A) in NLRP3 was archived in the COSMIC database from a lung adenocarcinoma tumor sample (TCGA-50-5941-01), and the nonsynonymous mutations of neither NLRP3 nor PBX1 were archived in dbSNP, 1,000 Genomes Project, ExAC database, and COSMIC." (PMID 36091765, 2022).